MIR6780A (microRNA 6780a)
Synonyms: hsa-mir-6780a
Gene: MicroRNA gene on chromosome 17 (42,708,084 to 42,708,151, reverse strand). Ensembl gene ENSG00000275273.
Homologues: Orthologues: chimpanzee MIR6780A (100% identical).